SESN1 (sestrin 1)
Diseases named in the same sentence as SESN1 in open-access papers (continued):
Sharing a sentence is not in itself a finding about the gene and the disease.
prostate carcinoma (3 papers, 2020 to 2021). A carcinoma that arises from epithelial cells of the prostate gland. "Although sestrin mutations are rare (≤0.8%), SESN1 deep deletion is a frequent event in prostate cancer occurring in 4.7–13.4% of cases, potentially leading to increased mTORC1 signaling through alleviation of SESN1-mediated negative regulation of mTORC1." (PMID 32630372, 2020). "Donor samples deemed to be G2 chromosomal radiosensitive (152 abs/100 meta) were our focus, because although CDKN1A, FDXR and SESN1 were clearly radiation-responsive genes, this was consistently observed in both healthy control and prostate cancer donors." (PMID 34638945, 2021). "Interestingly, similarly to FOXO3, SESN1 is located within the 6q21 locus that is commonly lost in prostate cancer." (PMID 32630372, 2020). "Thus, future work exploring the functional significance and predictive value of SESN1 depletion in prostate cancer could identify new therapeutic avenues or biomarkers to aid patient care." (PMID 32630372, 2020). "For the G2 radiosensitive prostate cancer donors, 60% (3/5) CDKN1A, 40% FDXR, 80% SESN1 and 40% PCNA gene expression exceeded the fold change threshold." (PMID 34638945, 2021). "First, the expression profiles of five key radiation-responsive genes (FDXR, SESN1, GADD45, DDB2, and MDM2) during the course of RT in the blood of 8 prostate cancer patients treated with IMRT and SABR were analyzed." (PMID 32519025, 2020). "Common genetic alterations within the three prostate cancer datasets analyzed were observed in PTEN, DEPTOR, SGK3, FOXO1/3, MAP3K7, RRAGD, SESN1, PIK3CA, PIK3C2B, and PDPK1." (PMID 32630372, 2020). "Similarly, correlations of clinical toxicity scores from prostate cancer donors were performed with G2 scores and gene expression of each individual gene PCNA, FXDR, CDKN12 and SESN1 using the non-parametric Spearmans correlation test." (PMID 34638945, 2021).
sarcopenia (3 papers, 2022 to 2023). Progressive decline in muscle mass due to aging which results in decreased functional capacity of muscles. "In addition, given that sestrin-1’s function is closely linked to the muscle, to reach more robust conclusions, it would have been useful to have data related to participants’ body composition and sarcopenia status." (PMID 35162104, 2022). "Sestrin 1 (Sesn1) was verified to be significantly downregulated in several models of muscle atrophy, including sarcopenia, and protect muscles against aging-induced atrophy." (PMID 36313746, 2022). "These clinical observations, together with our data, suggest that reduced secretion of myokine SESN1 may represent a potential predictive biomarker of muscle ageing, and an advance warning sign of sarcopenia." (PMID 37199024, 2023). "Among sestrin family members, sestrin-1 is characterized by strong expression in the skeletal muscle, and some studies have proposed that low levels of sestrin-1 may be a biomarker for sarcopenia or frailty." (PMID 35162104, 2022). "Interestingly, a recent study reported decreased SESN1 protein levels in serum of the elderly with sarcopenia relative to the elderly not afflicted with sarcopenia." (PMID 37199024, 2023).
COVID-19 (2 papers, 2020 to 2021). A disease caused by infection with severe acute respiratory syndrome coronavirus 2. "We confirmed that SREBP-2-induced cholesterol biosynthesis was suppressed by Sestrin-1 and PCSK9 expression, while the SREBP-2-induced inflammatory responses was upregulated in COVID-19 ICU patients." (PMID 32883951, 2020). "Moreover, SREBF2 mRNA, sestrin 1 (SESN1), and proprotein convertase subtilisin/kexin type 9 (PCSK9) RNA levels were increased in PBMCs in COVID-19 patients in a severity-dependent manner." (PMID 34944005, 2021). "However, according to the analysis, the mRNA expression levels of SESN1 and PCSK9, that suppress the lipid biosynthesis, were increased in the PBMCs of COVID-19 patients." (PMID 32883951, 2020).
liver fibrosis (2 papers, 2022). "No significant changes were observed in liver histology, biliary proliferation, and liver fibrosis in Sesn1−/−-sham vs." (PMID 34880414, 2022). "Consistently, hepatic expression levels of genes, including a progenitor cell marker (Sox9), a liver fibrosis marker (Acta2), and an inflammation marker (Il6), were decreased in Sesn1−/−-BDL vs." (PMID 34880414, 2022). "SESN1 mediates the effect of miR-200c on the proliferative and neuroendocrine-like capacity (of producing the mitogenic IL-6) of cholangiocytes and engages in the pathogenesis of liver fibrosis." (PMID 34880414, 2022). "A recent study demonstrated that loss of miR-200c accelerated intrahepatic inflammation and periductular fibrosis by targeting SESN1 and repressing the IL-6/AKT loop in cholestatic liver fibrosis models." (PMID 35662287, 2022).
melanoma (2 papers, 2011 to 2019). A malignant, usually aggressive tumor composed of atypical, neoplastic melanocytes. "Novel ORFs were identified in MCT4 and Sestrin-1 introns, with potentially critical roles in melanoma development." (PMID 30795533, 2019). "Conclusively, intron retention of Sestrin-1 may serve as a novel and reliable biomarker with important clinical value for melanoma diagnosis and therapy monitoring." (PMID 30795533, 2019). "Results: c-MYC and Sestrin-1 genes proved to undergo intron retention specifically in melanoma." (PMID 30795533, 2019). "Providing that not just the one identified in the present study, but all the introns of each gene transcript (c-MYC, MCT4, Sestrin-1, and SRPX2) can be potentially retained in human melanoma, next, we attempted to map their intronic landscapes for protein encoding sequences." (PMID 30795533, 2019). "Hence, a melanoma-specific demethylation mechanism that operates in a gene-dependent manner may compel the c-MYC, Sestrin-1, and SRPX2 transcripts to retain their introns, strongly suggesting an epigenetic control of splicing integrity." (PMID 30795533, 2019). "However, the strong expression levels of c-MYC (1564 bp), Sestrin-1 (1253 bp), and SRPX2 (1274 bp) irregular transcripts indicate their ability to escape the NMD quality control system operating in melanoma cells." (PMID 30795533, 2019). "Hence, providing that the Sestrin-1 intron-derived FKSG and FKSG-like novel proteins are indeed produced, as herein predicted, a network of “LLTS(F)Q”-dependent interactions among FKSG and FKSG-like superfamily members may be activated to potentiate the malignant character of melanoma." (PMID 30795533, 2019). "The collection of c-MYC, Sestrin-1, and SRPX2 nonspliced transcripts clearly typify human melanoma and molecularly differentiate it from BCC and SCC skin cancers." (PMID 30795533, 2019). "This c-MYC-dependent triggering of intron retention presumably compels the Sestrin-1 and SRPX2 genes to undergo a similar process of noncanonical splicing, likely providing melanoma cells with certain survival, growth, and motility advantages." (PMID 30795533, 2019).
neuroblastoma (2 papers, 2022 to 2024). Neuroblastoma (NB) is the most common solid, extracranial childhood tumor. "The results were consistent with overexpression of CCNE1, CDK2 or CHEK2 being worse prognostic factors, while increased regulation of SESN1 was a better prognostic factor in paediatric neuroblastoma." (PMID 35655142, 2022). "SESN1 was an independent prognostic factor of paediatric neuroblastoma in the TARGET, E-TABM-38, GSE49710 and GSE85047 datasets." (PMID 35655142, 2022). "In contrast, paediatric neuroblastoma patients with an age at diagnosis ≥ 18 months and SESN1 lower expression levels had a significantly worse prognosis." (PMID 35655142, 2022). "Combinations of CCNE1 with age at diagnosis or combinations of SESN1 with age at diagnosis achieved superior prognostic effects in paediatric neuroblastoma." (PMID 35655142, 2022). "Overall, age at diagnosis, MYCN amplification, CCNE1 and SESN1 were independent prognostic factors in at least four independent paediatric neuroblastoma cohorts." (PMID 35655142, 2022). "Paediatric neuroblastoma patients with an age at diagnosis ≥ 18 months and SESN1 higher expression levels had medium overall survival risks." (PMID 35655142, 2022). "In contrast to CCNE1, CDK2 and CHEK2, SESN1 had opposite expression levels and prognostic effects in paediatric neuroblastoma." (PMID 35655142, 2022).
neuroblastoma (continued). "SESN1 was also overexpressed in paediatric neuroblastoma patients with an age at diagnosis ≥ 18 months, and combinations of SESN1 expression with age at diagnosis achieved better prognostic effects in neuroblastoma." (PMID 35655142, 2022). "In contrast, SESN1 expression was downregulated in paediatric neuroblastoma patients with MYCN amplification in the TARGET, E-MTAB-161, E-MTAB-1781, E-MTAB-8248, E-TABM-38, GSE16476, GSE49710 and GSE85047 independent paediatric neuroblastoma cohorts." (PMID 35655142, 2022). "CCNE1 was also highly expressed in paediatric neuroblastoma patients with an age at diagnosis ≥ 18 months, while SESN1 was downregulated in paediatric neuroblastoma patients with an age at diagnosis ≥ 18 months." (PMID 35655142, 2022). "Paediatric neuroblastoma patients with an age at diagnosis < 18 months and SESN1 lower expression levels had the most diverse prognosis than other subgroups." (PMID 35655142, 2022). "We also observed superior prognostic effects in the combinations of SESN1 with age at diagnosis in paediatric neuroblastoma." (PMID 35655142, 2022). "Paediatric neuroblastoma patients with an age at diagnosis < 18 months and SESN1 higher expression levels had a significantly better prognosis." (PMID 35655142, 2022). "Higher expression of CCNE1, CDK2 or CHEK2 was an unfavourable prognostic factor, while higher expression of SESN1 was a favourable prognostic factor in paediatric neuroblastoma." (PMID 35655142, 2022). "Combinations of CCNE1 expression and SESN1 expression with age at diagnosis achieved a better prognosis of neuroblastoma." (PMID 35655142, 2022). "Combinations of CCNE1 and SESN1 with age at diagnosis achieved superior prognosis of neuroblastoma." (PMID 35655142, 2022). "However, the prognostic effects of CCNE1, CDK2, CHEK2 and SESN1 were different in paediatric neuroblastoma." (PMID 35655142, 2022). "SESN1 was downregulated in MYCN-amplified paediatric neuroblastoma patients, and SESN1 overexpression was associated with better clinical outcomes of paediatric neuroblastoma." (PMID 35655142, 2022). "Our results highlighted the new prognostic roles of SESN1 in paediatric neuroblastoma." (PMID 35655142, 2022). "However, overall survival was increased in paediatric neuroblastoma patients with high SESN1 expression in the TARGET, E-MTAB-161, E-MTAB-1781, E-MTAB-8248, E-TABM-38, GSE16476, GSE49710 and GSE85047 datasets." (PMID 35655142, 2022). "SESN1 is a downstream target of MYCN and functions as a new tumor suppressor gene via Toll‐like receptor signaling pathway in neuroblastoma." (PMID 38516781, 2024). "CCNE1, SESN1, MYCN amplification and age at diagnosis were independent prognostic markers of neuroblastoma." (PMID 35655142, 2022). "The mRNA expression levels of CCNE1, CDK2, CHEK2 and SESN1 in paediatric neuroblastoma patients with or without MYCN amplification were also investigated." (PMID 35655142, 2022). "However, the prognostic value of CHEK2 and SESN1 in paediatric neuroblastoma has never been reported." (PMID 35655142, 2022).
asthma (1 paper, 2026). "The remaining three IL-22 activators were all candidate genes for asthma alone: GNA15, SESN1, and GATA3, of which only GATA3 has been previously reported to directly activate IL-22 in ILC3s113." (PMID 41573945, 2026).
cholestasis (1 paper, 2022). Impairment of the bile flow caused by obstruction within the liver, or outside the liver in the bile duct system. "In this study, the function of SESN1 is prominent in the presence of cholestasis because SESN1 is induced by BAs in vitro and during cholestasis." (PMID 34880414, 2022). "On a molecular level, the pro-proliferative IL-6/AKT feedback loop was activated in Mir200c−/− livers but was inhibited in Sesn1−/− livers upon cholestasis in mice." (PMID 34880414, 2022). "In cholestasis, accumulated BAs result in the marked reduction of miR-200c and the subsequent increase of SESN1 in cholangiocytes, which contributes to the activation of the IL-6/AKT loop and increases ductular reaction, biliary hyperplasia, and biliary fibrosis." (PMID 34880414, 2022). "This demonstrates that the IL-6/AKT loop can be regulated by miR-200c/SESN1 during cholestasis." (PMID 34880414, 2022). "Examination of several signaling pathways revealed a striking elevation of p-AKT protein in Sesn1+/+-BDL, which was greatly dampened in Sesn1−/−-BDL livers, suggesting that SESN1 contributed to AKT activation in cholestasis." (PMID 34880414, 2022).
Cholestatic liver disease (1 paper, 2022). "These demonstrated a negative correlation between the expression levels of SESN1 and miR-200c in cholestatic liver diseases." (PMID 34880414, 2022).
coronary artery diseases (1 paper, 2020). "In a previous study, circulating Sesn1, Sesn2, and Sesn3 were reported to be increased in patients with coronary artery diseases, while the amplitude of the increase in Sesn levels was closely related to the degree of stenosis and oxidative stress in CAD patients." (PMID 32626541, 2020).
dermatitis (1 paper, 2019). An inflammatory process affecting the skin. "While the expression level of FDXR gene increased in patients experiencing a high grade of dermatitis radiation, those of SESN1, ATM, XPC, ZMAT3, CDKN1A genes decreased when radiation toxicity was manifested." (PMID 31632918, 2019). "In this prospective cohort study, we found that symptoms of dermatitis radiation, pain, pruritus and fatigue were associated with the expression level of some genes of the DNA-damage response pathway (FDXR, SESN1, XPC, ZMAT3, ATM, BCL2/BAX, and CDKN1A)." (PMID 31632918, 2019).
diabetes mellitus (1 paper, 2017). A metabolic disorder characterized by abnormally high blood sugar levels due to diminished production of insulin or insulin resistance/desensitization. "Based on the predicted target genes, miR-15a-5p could target the regulation of SESN1, as SESN1/AMPK also has the potential to prevent fibrosis of diabetes mellitus function." (PMID 29038788, 2017).
endometrial cancer (1 paper, 2019). Primary or metastatic malignant neoplasm involving the endometrium (mucous membrane that lines the endometrial cavity). "The co-transfection experiments of miR-200b, miR-200c, and miR-429 mimics or miR-NC with pLightSwitch_3′UTR reporter vectors containing the 3′UTR sequence of SESN1 revealed no significant change in luciferase activity in any of the analyzed endometrial cancer cell lines (Fig. 2a1–4)." (PMID 31073887, 2019).
hepatocellular carcinoma (1 paper, 2022). A malignant tumor that arises from hepatocytes. "Strikingly, the main features were the lack of CCL5+ B-cells in HS and the presence of SESN1+ B cells in HS with hepatocellular carcinoma (HS-HCC)." (PMID 35865544, 2022).
Huntington disease (1 paper, 2023). Huntington disease (HD) is a rare neurodegenerative disorder of the central nervous system characterized by unwanted choreatic movements, behavioral and psychiatric disturbances and dementia. "With minimal evidence in the literature for the novel miRNAs, miR-6715b-3p has been previously identified as integral in the modulation of autophagy through SESN1 targeting in Huntington’s disease and was also found to be downregulated in prostate adenocarcinomas." (PMID 37869015, 2023).